MET (MET proto-oncogene, receptor tyrosine kinase)
Diseases named in the same sentence as MET in open-access papers (continued):
Sharing a sentence is not in itself a finding about the gene and the disease.
gastric cancer (continued). "Despite the attenuated significance in the extension analysis, c-MET which is synonymous with HGFR (hepatocyte growth factor receptor) may be an independent risk gene for gastric cancer." (PMID 22383989, 2012). "Moreover, MET activation can also result from infection of gastric cells by Helicobacter Pylori, a known predisposing factor for development of gastric cancer." (PMID 20500904, 2010). "In our work we studied the molecular mechanisms that could cause resistance to therapies targeting MET in gastric cancer." (PMID 20500904, 2010). "However, the result of Kaplan–Meier Plot investigation specified that the MET gene deregulation can be regarded as a substantial diagnostic way in prognostic tool for identifying lung and gastric cancers patients because the plot showed less survival rate for them." (PMID 37200850, 2023). "In addition to aberrant upregulation, mutations of MET were also detected in gastric cancer and they may result in the activation of cell signaling transduction pathways." (PMID 23554766, 2012). "SATB1 is implicated in the upregulation of HER3 expression following MET inhibition, enhancing HRG/HER3 signaling and thereby allowing gastric cancer cells to evade the cytotoxic effects of MET-targeted therapies." (PMID 40071088, 2025). "This case further reinforces the importance of molecular profiling in guiding treatment decisions and underscores the urgent need for expanded clinical research on MET inhibitors in gastric cancer." (PMID 40860829, 2025). "EVs derived from stomach cancer cells encapsulate proteins such asclaudin-7, CD44v6, CD44, c-MET, EGFR, EpCAM, and GPC1, all of whichare closely associated with the progression of gastric cancer." (PMID 40720603, 2025). "No notable genetic alterations distinguishing the two groups were observed for other gastric cancer‐associated genes, such as BIRC5, MET, and MMP2." (PMID 41407509, 2025). "In a clinical trial targeting both EGFR and MET, amivantamab achieved a disease control rate of 26.1% in patients with gastric cancer and gastroesophageal junction cancer." (PMID 41361128, 2025). "Experimental silencing or knockout of Gal-4 in gastric cancer models has been shown to reduce the levels of activated c-MET and CD44, leading to attenuated cell proliferation and decreased peritoneal dissemination." (PMID 40710343, 2025). "Growing evidence supports the use of small-molecule MET or ERBB2 inhibitors in gastric cancer, particularly in molecularly defined subgroups with receptor overexpression." (PMID 40723172, 2025). "The mesenchymal-epithelial cell transition factor receptor (MET) is a receptor for hepatocyte growth factor (HGF) that can be amplified in gastric cancer." (PMID 40296904, 2025). "Scope of the Review: While MET mutations are most often observed in non-small cell lung cancer (NSCLC), they also occur in other malignancies, including breast and gastric cancers." (PMID 40361420, 2025). "This compound exhibited promising activity specifically targeting MET-amplified Hs746T gastric cancer cells in vitro." (PMID 38892160, 2024). "miR-34a is also a regulator of RTKs by affecting MET gene expression and plays a role in gastric cancer proliferation and metastasis." (PMID 38200584, 2024). "In gastric tumors, MET amplification has been reported in approximately 4-10% of patients while overexpression of c-Met protein is observed in 50% of advanced gastric cancers." (PMID 38634107, 2024). "Patients with advanced gastric cancer reportedly show alterations in c-MET expression after chemotherapy and worse outcomes in the c-MET+ group." (PMID 38238761, 2024). "Their efficacy has been evaluated in the EBC-1 NSCLC cell line (c-MET overexpression) and the Hs746T gastric cancer cell line (MET exon 14 skipping)." (PMID 39456995, 2024). "Inhibitors of c-MET showed potent anti-tumor activity against various cancers, including gastric cancer and hepatocellular carcinoma (HCC)." (PMID 39458991, 2024).
gastric cancer (continued). "The expression of c-MET in circulating monocytes of gastric cancer patients was identified, with monocyte-derived dendritic cells exposed to HGF exhibiting a regulatory phenotype." (PMID 39664377, 2024). "Other researchers reported the overexpression of FGFR2 as an intrinsic resistance to MET inhibitors with patient-derived gastric cancer xenograft models." (PMID 38892160, 2024). "Treatment with emibetuzumab induces reductions in phosphorylated and total c-MET levels, leading to the inhibition of cell proliferation and tumor growth in gastric cancer cell lines (MKN-45 and SNU-5) as well as in NSCLC cell lines (EBC-1 and H1993)." (PMID 39664377, 2024). "Previously, TPR-MET was the only recognized MET gene rearrangement in human tumors predominantly found in gastric cancers." (PMID 38675409, 2024). "Within this context, RNA-sequencing analysis in gastric cancer uncovered a link between macrophage-derived IL-10 and the activation of c-MET/STAT3 signaling pathways." (PMID 39664377, 2024). "Their findings revealed that gastric cancer cells release phosphorylated mesenchymal-epithelial factor (p-MET) following H. pylori infection." (PMID 39726601, 2024). "In MET‐CAR T co‐cultured organoids derived from gastric carcinoma patients, MET‐CAR T cells exhibited improved immunotherapy efficacy against MET‐amplified tumour cells and organoids." (PMID 39245957, 2024). "The clinical analysis discovered several consequences of MET gene deregulation in various kinds of cancers, i.e., lung, breast, ovarian, and gastric cancer." (PMID 37200850, 2023). "Although most patients had mutually exclusive FGFR2 or MET amplifications, two (0.3%) gastric cancer patients had both FGFR2 and MET amplifications detected in the same tumor specimen using NGS." (PMID 38137393, 2023). "Overall, results are encouraging thus far, and further studies are warranted to fully elucidate the role of c-MET and targeted therapy in gastric cancer." (PMID 37877107, 2023). "We tried to find the concurrent amplification of FGFR2 and MET in gastric cancer through a search in public cohort data (cbioportal.org), but we were unable to find it." (PMID 38137393, 2023). "Activation of MET in gastric cancer is thought to be primarily a result of receptor overexpression and/or genomic upregulation (amplification/fusion)." (PMID 37046637, 2023). "Initially, the NGS was tested in a primary tumor specimen from stomach cancer, where the MET copy number was 14.1 and the FGFR2 copy number was 5.3." (PMID 38137393, 2023). "has revealed that the IFITM3 can expand malignant progression, promote cancer stemness and chemoresistance of gastric cancer by targeting MET/AKT/FOXO3/c-MYC axis." (PMID 37304304, 2023). "The VIKTORY UMBRELLA trial is a basket study of patients with gastric cancer based on clinical sequencing and focuses on eight different biomarker groups of which MET amplification and MET overexpression (IHC 3+) are two." (PMID 37046637, 2023). "The first relation between cMET and gastric cancer (GC) was described in 1992 in eleven gastric cell lines that showed the presence of MET amplification on chromosome 7 in mostly diffuse type gastric cancer and was indicative of poor prognosis." (PMID 37046637, 2023). "Background: c-mesenchymal epithelial transition factor receptor (c-MET) and fibroblast growth factor receptor 2 (FGFR2) amplification have been identified as factors associated with advanced stage and poor prognosis in gastric cancer (GC)." (PMID 38137393, 2023). "The tepotinib PK/PD relationship was first investigated in a single-administration study, using the Hs746T gastric cancer model (harboring METex14 skipping and METamp) with constitutive MET phosphorylation." (PMID 36999986, 2023). "One further biomarker that is also a member of the receptor tyrosine kinase family and is expressed in a significant proportion of gastric cancer biopsies is c-mesenchymal epithelial transition factor (c-MET)." (PMID 37877107, 2023).
gastric cancer (continued). "Over the years, different methods have been developed to detect MET overexpression and/or amplification in gastric cancer, all of which have their advantages/disadvantages." (PMID 37046637, 2023). "Several investigator-sponsored studies are also underway in patients with cancers with MET alterations, including gastric cancer (NCT05439993) and brain tumors (NCT05120960)." (PMID 36999986, 2023). "Strong MET inhibition was also observed in the gastric cancer cell lines Hs746T (harboring METex14 skipping and high-level METamp) and GTL-16 (harboring high-level METamp), with IC50 values of 2.5 and 2.9 nmol/L, respectively." (PMID 36999986, 2023). "The identification of c-MET as a molecular biomarker in gastric cancer has been correlated with a poor prognosis." (PMID 37877107, 2023). "The overexpression or amplification of c-MET is evident in gastric cancer, which helps to promote tumour cell growth, angiogenesis, metastasis, and survival." (PMID 37877107, 2023). "According to the results of the clinical investigation through Kaplan–Meier, MET gene deregulation was correlated with the survival rate of lung and gastric cancer patients." (PMID 37200850, 2023). "Comprehensive molecular characterization in gastric cancer revealed by mRNA sequencing alternative splicing events of the MET 2 exon showed skipping in 30% of cases, which also resulted in MET overexpression." (PMID 37046637, 2023). "While gene amplification of MET is infrequent in gastric cancer p”Iie’ts (4–10%), an overexpression of the c-MET protein has been identified in a significant proportion of cases, ranging from 18% to 82%." (PMID 37894443, 2023). "Of note, a 43-year-old man with gastric cancer and peritoneal seeding, who had MET amplification, showed a mixed response to the MET inhibitor." (PMID 38137393, 2023). "Following the success of HER-2-targeted therapy in HER-2 positive gastric cancer, several monoclonal antibodies and small molecules targeting other RTKs such as MET and FGFR2, along with their downstream signaling pathways, have been investigated." (PMID 38137393, 2023). "Following the strong inactivation of YAP1 observed in LoVo cells, we decided to evaluate YAP1 localization and protein levels also in an additional MET-dependent gastric carcinoma model, GTL16." (PMID 37838732, 2023). "They found that PD-L1-CPS (combined positive score) and PD-L1-TPS (tumor cell positive score) in gastric cancer tissues were positively correlated with c-MET protein expression (r values of 0.496 and 0.317, P < .01)." (PMID 36482562, 2022). "At the same time, there was a significant association between tumor budding and MET status, but in contrast to HER-2 and MSI, gastric cancer with a high budding grade tended to be MET-positive more frequently than tumors with a low budding grade." (PMID 36755859, 2022). "The results of previous studies have shown that high expression of MET gene predicts a poor prognosis of gastric cancer, which is consistent with our findings." (PMID 35659682, 2022). "This case report provides evidence for MET tyrosine kinase inhibitors in treating gastric cancer patients with MET gene amplification." (PMID 36482562, 2022). "Previous studies indicated that elevated doses of crizotinib can induce autophagy in alveolar rhabdomyosarcoma cells and that autophagy is required for crizotinib-induced apoptosis in MET-amplified gastric cancer cells." (PMID 35118587, 2022). "Aberrant MET genes appeared in various cancers in the following order: gastric cancer (N = 17, 32.1%), colorectal cancer (N = 11, 20.8%), and CCC (N = 7, 13.2%)." (PMID 36483096, 2022). "The overexpression of cellular-mesenchymal epithelial transition (c-MET) is one of the mechanisms of cisplatin resistance in gastric cancer." (PMID 35155421, 2022). "MET amplification has been proposed as a resistance mechanism against HER2 therapy in gastric cancer." (PMID 35650563, 2022).
gastric cancer (continued). "This case report of a 35-year-old male with advanced gastric cancer, with bone and bilateral adrenal metastasis, MET gene amplification, and intolerance to conventional chemotherapy responded well with savolitinib treatment." (PMID 36482562, 2022). "Similar to the finding of previous studies, we demonstrated that there was a concomitant overexpression of MET and HER2 in a subset of patients with gastric cancers, suggesting the feasibility of dual blocking of MET and HER2." (PMID 34557411, 2021). "We demonstrated that MET protein expression is altered post chemotherapy in advanced gastric cancer." (PMID 34557411, 2021). "MKN45 cell line was featured as MET and phosphorylated MET (pMET) high expressions compared to other gastric cancer cells, which was chosen to explore the efficacy of volitinib in vivo and the possible mechanisms." (PMID 34557411, 2021). "The observed results herein indicated MET involvement in resistance of lung, bladder, and gastric cancer cells to CPL304110." (PMID 33898310, 2021). "In MET-positive gastric cancer cell lines, H. pylori infection upregulates MET phosphorylation, and its downstream signals, such as p44/42 MAPK and Akt, are activated and confer gastric cancer cells upon proliferation and anti-apoptotic activities." (PMID 34436224, 2021). "Exosome-delivered MET-specific siRNA (exo-si-c-Met) reversed resistance to cisplatin in gastric cancer cells in vivo and in vitro." (PMID 33526881, 2021). "A systematic review and meta-analysis showed that MET overexpression and gene amplification in tumor tissue were indicators of poor prognosis in patients with gastric cancer." (PMID 33959414, 2021). "The abnormally increased expression of the N short-truncated MET isoform had also been observed in gastric cancer." (PMID 35111672, 2021). "Repeating this analysis in a second independent cohort of 20 pairs of gastric cancer samples re-identified MET and FGFR4 as upregulated in GC samples (left)." (PMID 33482911, 2021). "RDO24 mAb recognized the surface MET protein expressed in different types of human cells: GTL16 gastric carcinoma, A549 lung adenocarcinoma, HEK293T human embryonic kidney cells, and HUVEC human umbilical vein endothelial cells." (PMID 34925346, 2021). "In MET overactive (as a result of MET amplification and constitutive activation) gastric carcinoma cells and lung squamous cells treated to be resistant to MET-TKI, miR-205 is epigenetically induced." (PMID 34206547, 2021). "In the present study, tissue microarrays containing gastric cancer tissues were stained with MET and AXL antibodies, which showed the prognostic values of MET and AXL." (PMID 34766112, 2020). "It has been reported that H. pylori infection in gastric cancer cells increases the production of exosomes that contain the active form of MET." (PMID 33217986, 2020). "MET inhibitor showed high response rate (50%) in a genomic matched trial of gastric cancer, which indicates that MET inhibitor can be considered for tumors with MET amplification." (PMID 32813918, 2020). "Genomic alterations in RTKs, including EGFR, HER2, FGFR2, and MET, were reported to occur in ~37% of gastric cancer patients." (PMID 32005975, 2020). "Dephosphorylated MET was found to promote autophagy in liver cancer and gastric cancer, suggesting that a combination of kinase activity-targeted drugs and autophagy inhibitors is a potential treatment strategy." (PMID 33204717, 2020). "Smolen et al61 found that only a fraction of gastric cancer cell lines appeared to be extraordinarily vulnerable to the selective MET inhibitor PHA‐665752, and these cells were found to have high‐level amplification of wild‐type MET." (PMID 34766112, 2020).
gastric cancer (continued). "Our findings indicate that ASTX can suppress H. pylori-induced gastric cancer progression by inhibiting cytoskeleton reorganization and reducing cell motility through downregulation of c-MET, EGFR, PI3KC2, PLCγ1, Cdc42, and ROCK1." (PMID 32679742, 2020). "In silico analysis of the TCGA and GEO database found that HGF and c-MET mRNA expression are significantly higher in gastric cancer tissues than those in peritumor tissues." (PMID 32788873, 2020). "In our study, analysis of a panel of seven gastric cancer cell lines using qPCR‐identified increased MET gene copy number only in MKN45 cells, which was further validated at the protein level by Western blot analysis." (PMID 34766112, 2020). "In gastric cancer, >10% of patients show MET amplification and approximately 40% show MET protein overexpression." (PMID 32549194, 2020). "In this study, we address the functional relevance of HER receptors, and in particular of HER3, in MET-amplified gastric cancer cell lines." (PMID 33374770, 2020). "In conclusion, ASTX can suppress H. pylori-induced gastric cancer progression by inhibiting cytoskeleton reorganization and reducing cell motility through downregulation of c-MET, EGFR, PI3KC2, PLCγ1, Cdc42, and ROCK1." (PMID 32679742, 2020). "In the present study, we demonstrate that treatment of MET-amplified gastric cancer cells with a MET inhibitor leads to a SATB1-mediated upregulation of HER3." (PMID 33374770, 2020). "It has been shown previously that MET inhibition in monocultured gastric cancer cells with MET amplification exerts dramatic anti-proliferative effects, in parallel with abrogation of ERK and Akt phosphorylation." (PMID 33374770, 2020). "We performed this study to evaluate the antitumor impact of LY2801653, a dual MET and AXL inhibitor on gastric cancer and to elucidate the underlying mechanisms." (PMID 34766112, 2020). "Recently, targeted therapies against oncogenic receptor tyrosine kinases (RTKs), e.g., FGFR, HER1, HER2, HER3, or MET, have been tested in patients with gastric cancer." (PMID 33374770, 2020). "This establishes the role of HRG/HER3 signaling in mediating resistance of gastric cancer cells towards MET inhibition." (PMID 33374770, 2020). "Concomitantly, SATB1 knockdown abrogated the HRG-promoted rescue of gastric cancer cells after MET inhibition." (PMID 33374770, 2020). "Heregulin can activate HER3-promoted signaling pathways via HER1/HER3 or HER2/HER3 heterodimers; however, it has not been elucidated so far which of these heterodimers mediate these pro-survival effects in MET addicted gastric cancer cells." (PMID 33374770, 2020). "This study aimed to elucidate the expression level of HGF-c-MET in gastric cancer patients and to investigate the prognostic and diagnostic value of HGF-c-MET." (PMID 32788873, 2020). "The mutation of HGF and mRNA upregulation of c-MET were the most common type of HGF and c-MET gene alterations in gastric cancer database, respectively." (PMID 32788873, 2020). "MET-amplified gastric cancer cells are extremely sensitive to MET inhibition in vitro, whereas clinical efficacy of MET inhibitors is disappointing." (PMID 33374770, 2020). "Discrepancies between preclinical data and the clinical reality are particularly striking in the case of the inhibition of the HGF/MET axis in gastric cancer cells harboring a MET amplification, which occurs in 3–7% of gastric tumors." (PMID 33374770, 2020). "The Wnt/β-catenin, HGF/c-MET, and Ras/Erk pathways have been associated with numerous cancers and mediate EMT in gastric cancer (GC)." (PMID 32825724, 2020). "Overexpression of HGF mRNA and/or protein, MET mRNA and c-MET protein have been recorded in 20-30%, and 40-70% samples of gastric cancer patients, respectively 14, 28, which were higher than the proportion of gastric cancer dataset based on TCGA database." (PMID 32788873, 2020).